TNF (tumor necrosis factor)
Diseases named in the same sentence as TNF in open-access papers (continued):
Sharing a sentence is not in itself a finding about the gene and the disease.
infection (continued). "During infection, MG interacts with host respiratory epithelial cells and generates an inflammatory response, resulting in increased levels of cytokines, such as tumor necrosis factor alpha (TNF-α), interleukin-6 (IL-6), and interleukin-2 (IL-2)." (PMID 29652844, 2018). "However, the concentrations of interferon (IFN) γ, tumour necrosis factor (TNF) α, interleukin (IL) 6, and IL-10 were significantly elevated due to infection with T. gondii alone, whilst the levels of IL-1α were down-regulated compared with other groups." (PMID 30186279, 2018). "At later timepoints following infection (weeks 16 and 22), therapeutic immunization induced a significantly higher frequency of CD4+ T cells producing CD154, GM-CSF, IFN-γ, IL-2, and TNF-α at 16 and 22 weeks post infection compared to RHZ-treated mice with ex vivo ID93 antigen stimulation." (PMID 29795025, 2018). "Interestingly, dual deletion of genes 4a and 4b led to a significant increase in the expression levels of IL-6, IL-8, and TNF-α as compared to the wild-type infection." (PMID 29370303, 2018). "Furthermore, plasma levels of inflammatory mediators interleukin-6 (IL-6), CXCL-1, and tumor necrosis factor (TNF) were significantly lower in C5ar1−/− mice than in WT mice at 12 h of infection." (PMID 29362231, 2018). "Moreover, the secretions of TNF-α and IL-6 in culture supernatants after Mab infection were also decreased by pretreatment with SdLv in a concentration-dependent manner." (PMID 30452471, 2018). "Unsurprisingly, in the slower moving L. major infection we did not see a significant decline of the numbers of KC nor did we detect a significant genotype-dependent changes between B6.WT and B6.TNF−/− during the course of infection (with the exception of day 21 after infection)." (PMID 29403488, 2018). "In a meta-analysis of 21 studies enrolling 5356 CD patients, Peyrin–Biroulet and colleagues reported that anti-TNF therapy did not significantly increase the risk of death, malignancy, or serious infection when compared with placebo." (PMID 30065229, 2018). "Because the trend of infection and the TNF effect were shown to be similar in both of the assays, that FACS assay could be applicable for internalization and intracellular growth evaluation in c-fos siRNA-treated cells." (PMID 30186773, 2018). "Also, IL-6 and TNFα has been shown to facilitate infection of resting CD4+ T-cells and to induce productive infection." (PMID 29997630, 2018). "Based on these findings we hypothesize that the activated microglia in μBS play a potential role in enhancing the expression of pro-inflammatory cytokines such as interleukin (IL)-1β, IL-6, and TNF-α in response to ZIKV-BR infection." (PMID 30619100, 2018). "Moreover, the in vitro stimulation of splenocytes obtained from mice after 7 days of infection with ultraviolet (UV)-inactivated ZIKV demonstrated an expansion of CD8+ T cells expressing TNF, when compared to the cells obtained from uninfected control mice." (PMID 30087337, 2018). "In vivo, exogenous Nef and TNF secreted by infected cells as soluble proteins and/or as exosomes can activate uninfected CD4+ T cells and MDMs present in the vicinity and make them susceptible to infection." (PMID 29652795, 2018). "Furthermore, L-GSH has significant downregulating effects on the production of TNF-α at day 8 compared to 15 days post-infection." (PMID 29494546, 2018). "Compared with VR2332c or mock infection, JA142c induced increased levels of type I interferons and pro-inflammatory cytokines (TNF-α, IL-1α/β, IL-6, IL-8, and IL-12) in PAMs, and these elevated levels were comparable to the cytokine induction observed in PRRSV-challenged pigs." (PMID 30509265, 2018). "While the ST1 strain P1/7 and the ST25 strain 89-1591 both induced a variety of cytokines following infection of murine DCs (TNF, IL-6, IL-12p70, and CXCL1), only levels of IL-6 and CXCL1 induced by P1/7 (ST1) were significantly higher than those induced by 89–1591 (ST25) (p < 0.01)." (PMID 30001363, 2018).
infection (continued). "The TNF degradation rate constant (kDeg) and a scaling factor that accounts for the coarse-grained TNF dynamics (estConsRateTNF) only significantly affect bacterial levels after ~50–60 days post infection." (PMID 31258937, 2018). "In addition, infections are a concern in patients treated with anti-TNF-α agents and the long-term side effects of controlling the immune system are not yet fully understood." (PMID 30412634, 2018). "Indeed, in the anti-TNF-α group the infection rate was 01.68 serious infections per patient year vs. 0.149 in the control patients (p = 0.886)." (PMID 30060508, 2018). "However, TNF-α serum levels in individuals with a medium to high parasite load (≥100 epg) were significantly higher than in the group with a low intensity of infection (4–99 epg)." (PMID 30619332, 2018). "Similarly, OT-II cells expressing both TNFα and IFNγ significantly increased in LdWT (p = 0.0422) and LdCen−/− (p = 0.0448) infections upon blocking with α-CD200 antibodies." (PMID 29915577, 2018). "Recognition of T. cruzi by the innate and adaptive immune cells trigger the production of cytokines, such as IL-1β, IL-18, IL-6, TNF, and IL-10 during the acute phase of infection which exert profound effects in the killing of parasites and in the modulation of inflammation." (PMID 29774028, 2018). "TNF-a levels were increased by PAO1 infection, but independently of the presence of LasB." (PMID 30083156, 2018). "Contrastingly, BMDM produced high levels of TNF-α upon WSN infection." (PMID 29867955, 2018). "Such variety of activities may provide poxviruses the ability to differentially block chemokines involved in distinct anti-viral responses, to inhibit chemokines at different stages of infection in the host or to simultaneously inhibit chemokines and TNF." (PMID 29724993, 2018). "Moreover, CARD9 deficiency completely blocked AM accumulation and significantly reduced secretion of pro-inflammatory cytokine including TNF-α and IL-6 in the lungs on day 1 after infection with C.g-B." (PMID 30131805, 2018). "In the present investigation, secretion of IL-10 was present in infected animals, but was more reduced by the F3 than by the NH36 vaccine, as observed by their respective IFN-γ/IL-10 and TNF-α/IL-10 ratios, which characterize a Th1 response against the infection." (PMID 29867949, 2018). "When stimulating polyp epithelial cells with TNF-α, mimicking infection, ICAM1 was upregulated." (PMID 29367682, 2018). "Severe IV infection induces many cytokines; IFNαβ, TNFα, IFNγ, C-X-C motif chemokine (CXCL) 10 (CXCL10), CXCL9, C-C motif ligand (CCL) 2 (CCL2), CCL4, CCL5 and interleukin (IL)−6 (IL-6), IL-2, IL-8, and IL-10 have all be observed to be upregulated during severe IV infection in humans." (PMID 30250466, 2018). "However, we do observe CD154, IFN-γ, IL-2, and TNF expression from the RHZ+ID93/GLA-SE groups as early as seven weeks post infection." (PMID 29795025, 2018). "However, as we did not specifically address the mechanism in the course of this study, future work will focus on clarifying the role of TNF-α in infection-mediated EGFR upregulation." (PMID 30524196, 2018). "Similarly, mOasl2 significantly enhanced the expression of RNase L and six (IRF3, IFNα, IFNβ, IFIT1, IL8, and TNFα) of 10 tested genes related to IFN signaling in A549 cells after infection by the PR8 virus." (PMID 29973937, 2018). "Nevertheless, infection experiments using L. major, specifically the BNI substrain, and other intracellular pathogens demonstrated a strong protective effect of TNF since L. major BNI infected TNF-deficient mice succumbed rapidly to the parasites despite a strong Th1-type response." (PMID 29403488, 2018). "It should be noted that for IFN-γ, KC, and TNF-α, we are able to measure these cytokines in the serum at levels greater than prebleed at 21, 28, and 57 dpi; however, the level of expression is low compared to expression during acute infection." (PMID 30333181, 2018).
infection (continued). "It is also known that HIF-1 expression is upregulated in response to inflammatory stimuli including IL-1β, TNF, and bacterial products through pathways involving NF-kB, highlighting an interdependence of the innate immune and hypoxic responses to infection and tissue damage." (PMID 30250643, 2018). "We demonstrate that neutralization of soluble TNFα (sTNFα) by the anti-TNFα Abs Humira®, Remicade®, and its biosimilar Remsima® negatively affects infection as treatment with these agents significantly reduces Leishmania-induced T-cell proliferation and increases the number of infected macrophages." (PMID 30108591, 2018). "Interestingly, human Babesia WA1 parasites infection in mice resulted in upregulation of both TNFα and IFNγ resulting in severe pathogenesis and fatal disease." (PMID 29445365, 2018). "In contrast, a dose of 10 mg/L INH/RIF provided a partial protection, with a survival delayed by one week, reduced body weight loss and bacterial burden on day 32, while 100 mg/L INH/RIF on day 14 to 35 allowed TNFα−/− mice to survive up to 78 days post-infection with controlled bacterial burden." (PMID 29872095, 2018). "Hence, we quantified the levels of IL-6, TNF-α, and, IL-1β in plasma obtained from intravenous infection model mice." (PMID 30251911, 2018). "TNF-α, another proinflammatory cytokine, is primarily produced by macrophages, and is essential in fostering the formation and maintenance of a granuloma in both acute and chronic phases of infection." (PMID 30258443, 2018). "TNF-α is a proinflammatory cytokine that regulates the immune system and promotes a response capable of eradicating infectious agents, but can also lead to local injury at the site of infection and harmful systemic effects." (PMID 30400258, 2018). "As a result, the downregulated IL18R may decrease the secretion of TNFα after infection via NF-κB signaling." (PMID 30258450, 2018). "Interestingly, when the infection reaches high fungal burden levels, Lin−-derived macrophages become tolerized, as they have a diminished ability to produce TNF-α, whereas they keep up their fungicidal capacity." (PMID 30234030, 2018). "Our finding that TNF is crucial for the maintenance of CD169+ cells in spleen tissue may be important for infections with lower doses of virus, because allowing viral replication in CD169+ cells is particularly important for protective adaptive immunity." (PMID 29142134, 2018). "For example, ligation of CR3 by the surface virulent factor BAD1 of Blastomycetes dermatitidis results in TNF suppression and immune invasion, and infection of murine macrophages with Mycobacterium avium in C3-depleted medium resulted in a significantly higher level of TNF production." (PMID 29632532, 2018). "We found rises in IFN-gama, TNF-alpha and IL-6 at 9 day after infection in all infected groups as compared to uninfected mice but only Bz displayed statistically significant lower (p = 0.02) TNF-alpha levels, possibly due to reduced parasitism levels and respective antigenic stimuli." (PMID 30186314, 2018). "In severe infection, the increased release of thrombopoietin and numerous inflammatory cytokines (e.g., interleukin-1, -3 and -6 and tumor necrosis factor-α) result in increased thrombopoiesis and an enhanced expression of younger large platelets into the bloodstream." (PMID 30533065, 2018). "As for TNF-α, the IL-17A and IL-22 increases were likely related to the magnitude of the bacterial burden and stimulus, and they were apparently unable to improve the course of infection." (PMID 30045763, 2018). "It is important to note that the infiltrating cells are probably contributing to an increased expression of cytokines, and thus chemokine blockade by the CrmD SECRET domain expressed in ECTVRevSECRET infections may impair localized TNF expression." (PMID 29724993, 2018).
infection (continued). "TLR3 deficiency in mice led to increased synthesis of TNF-α, IFN-γ, and IL-10; however, IFN-β, IL-1β, and IL-6 were secreted into the genital tracts of wild-type mice at significantly higher levels than in TLR3-/- mice during early infection." (PMID 29624589, 2018). "Similarly, cured patients, in particular, showed a higher frequency of CD8+ T cells expressing IFN-γ+ and TNF-α+ than did patients with active CL, suggesting a relevant role of these cytokines in infection control." (PMID 30510917, 2018). "Altenatively, it can be hypothesized that in order to combat infection, the synthesis of Pser is decreased in microglial cells that allows for an increase in the production of NO and TNF-α." (PMID 30359409, 2018). "To further investigate whether miR-181a-5p can influence TNF-α expression in BMDMs during B. abortus infection, we transfected macrophages with the specific mimic or inhibitor for mmu-miR-181a-5p before infection." (PMID 29942317, 2018). "TNF-α is, in part, produced by TcR-ɣδ+ T cells and its expression was shown to be increased in the jejunum of infected piglets, thus it might be more relevant and consequently TNF-α producing cells might be more abundant at the site of infection." (PMID 29973271, 2018). "The progressive infection that was caused by the absence of TNF was accompanied by a strong increase in the proportion of Mo-Ms that showed clear signs of alternative activation." (PMID 29403488, 2018). "Thus, O. tsutsugamushi inhibits TNFα-stimulated p65 accumulation in the nucleus and its ability to do so increases as infection proceeds." (PMID 29734393, 2018). "We also measured the levels of pro-inflammatory cytokines IFNγ, TNFα, IL-12, and IL-1β in cultured supernatant collected after 24, 48, and 72 h post infection to verify if the levels of these cytokines have any correlation with CD200 expression in parasite-infected DCs." (PMID 29915577, 2018). "A lower frequency of EBV-specific IFN-γ+/TNF-α+ CD4+ T cells has been described in HIV+ patients at early stages of infection and under ART when compared to that of responses to CMV and Mycobacterium tuberculosis, which are superior in frequency and multifunctionality." (PMID 30337929, 2018). "We started by studying the interplay of hypoxia and infection on the secretion of IL-6 and TNF-α." (PMID 30463908, 2018). "The absence of tumor necrosis factor (TNF) causes lethal infection by Leishmania major in normally resistant C57BL/6J (B6.WT) mice." (PMID 29403488, 2018). "However, in more complex in vivo infection models, the well-defined role of TNF in the iNOS-inducing cytokine network determined in vitro became controversial while the central effector role of NO remained undisputed." (PMID 29403488, 2018). "Because infection by different pathogens has variable effects on serum TNF-α and IFN-γ levels, the finding could be helpful in developing novel diagnostic methods." (PMID 30275916, 2018). "This hypothesis arises from the observation that low CD18 expression has a significant impact on the production of TNF-α in the lung early after infection." (PMID 30233576, 2018). "Indeed, TNF is an early response cytokine that plays a crucial role in recruiting innate immune cells to sites of infection and promoting microbicidal activities." (PMID 30050534, 2018). "Similarly, type 1 cytokines such as IFNγ and TNFα are generally present at similar levels in tissues after antibiotics treatment in uninfected mice but reduced at the site of infection in microbiota-depleted mice." (PMID 30429801, 2018). "It is generally accepted that macrophage activation by cytokines, such as IFN-γ and TNF-α, is important for eradication of Salmonella in experimental infection as these cytokines stimulate NK cells and macrophage effector mechanisms and later ensure T-cell response for pathogen clearance." (PMID 30186241, 2018).
infection (continued). "Also, by using specific inhibitors against ERK1/2, p38, and JNK, we observed that inhibition of all three MAPK pathways significantly decreased the infection-induced upregulation of proinflammatory cytokines IL-6, IL-8, IL-Iβ, and TNF-α." (PMID 30340642, 2018). "Regarding inflammation, infection of MT increased TNF-α, IL-6 and IL-8 expression." (PMID 30297793, 2018). "In the present study, we tested the hypothesis that therapeutic TNFα inhibitors, varying in their amino acid sequence or structure, differently influence Leishmania major (Lm) infection control." (PMID 30108591, 2018). "Likewise, the other type 1 cytokine, tumor necrosis factor (TNF) α can also act as a defensive factor against MTb infection through the maintenance of the granuloma." (PMID 30427928, 2018). "While proinflammatory cytokines such as TNF-α and IL-6 are distributed early on during the acute stage of an injury or tissue infection, chemokines like R/C may be activated at a later time." (PMID 30174768, 2018). "In PAD patients, pro-inflammatory IL-1β or TNF-α, and endotoxins, are frequently increased as a consequence of the inflammation and infection at the level of the foot, and these cytokines may stimulate SOCS proteins, promoting a GH insensibility." (PMID 29346331, 2018). "The indication of anti-TNF agents for elderly IBD patients is similar to that for young IBD patients, but there is a report that the response to the therapy is lower and the risk of serious infection and death is higher in elderly patients than young patients." (PMID 29429045, 2018). "Besides, as compared to the WT strain, the mutant induced less TNF-α and IL-12p40 release in the peripheral blood of the infected mice throughout the entire infection process." (PMID 29598830, 2018). "At 24 hours after infection, serum levels of Il-6, IL-17, IL-10, TNFα and IL1β were unchanged and while the levels of Il-6, IL-10, TNFα and IL1β increased in Ddx3xfl/y Vav-iCre relative to control animals at 72h, the difference only reached significance in the case of IL-10." (PMID 30475900, 2018). "On one hand, proinflammatory cytokines (e.g., IL-1α, IL-2, and TNF-α) are necessary to initiate the inflammatory response during infection, but the overexpression of such cytokines may lead to pathological responses." (PMID 30627122, 2018). "We have shown that the initial genomic response to infection of human cells with M. tuberculosis is a short-lived burst with increased production of mRNA transcripts coding for inflammatory cytokines, including TNF-α, IL-6, IL-8, MIP-1α and MCP-1." (PMID 29330469, 2018). "The executive functions of TNF exceed multiple disciplines as TNF is important in homeostatic processes as well as in pathological situations ranging from inflammation, neurodegenerative diseases and infections." (PMID 29751683, 2018). "Additionally, A28006 strain infection led to increased amounts of TNF-α and IL-12, as well as microbicidal NO, compared to the amounts induced by A54970 infection." (PMID 30518854, 2018). "This situation may be compounded in states of infection and systemic inflammation when hepcidin levels are increased by cytokines such as interleukin-6, tumor necrosis factor-α (TNF-α), and interleukin-1." (PMID 29382128, 2018). "Interestingly, neutral sphingomyelinase (NSM) and ASM are activated in response to various stress stimuli, including hydrogen peroxide, hypoxia, TNF‐α, and infection." (PMID 30389666, 2018). "In contrast, the infection induced effector non-protective Th1 response that highly expresses TNF-α, which has been implicated in the severity of skin lesions." (PMID 29946313, 2018). "Reactivation of an established infection, due to late administration of anti-TNFα antibodies, could be successfully controlled by antibiotics, but full clearance of the bacterial load from the tissues was not achieved." (PMID 28087648, 2017).